STAT3 (signal transducer and activator of transcription 3)
Diseases named in the same sentence as STAT3 in open-access papers (continued):
Sharing a sentence is not in itself a finding about the gene and the disease.
hepatocellular carcinoma (continued). "From a molecular perspective, it is important to note that, given the dissociation between STAT-1 and STAT-3 activation pathways, obesity may contribute to the development of NASH and hepatocellular carcinoma (HCC) through different independent mechanisms." (PMID 38248843, 2024). "The present study verified that curcumin could inhibit the growth of hepatocellular carcinoma cells, and the main mechanisms are apoptosis induction, cell cycle arrest, and downregulation of the expression of cell signal transduction pathways HIF-1α/STAT3/VEGF." (PMID 37333486, 2023). "STAT3 is one of the main regulators of SALL4 in breast cancer and hepatocellular carcinoma (HCC)." (PMID 36010677, 2022). "Deficiency of PTPN2 in hepatocytes resulted in maladjustment of signal transduction and activation of transcription 1 (STAT1) and STAT3, which eventually accelerated the progression on the spectrum of steatosis-NASH-cirrhosis-hepatocellular carcinoma (HCC) in mice." (PMID 35269812, 2022). "Our study explores the regulatory role of GNAS during STAT3 phosphorylation in HCC cells and demonstrates that GNAS promotes STAT3 Y705 phosphorylation by inhibiting TPTEP1 binding to STAT3, which mediates inflammation-induced hepatocellular carcinoma cell lines’ proliferation and invasion." (PMID 32123532, 2020). "In line with this, the STAT3/IL-6 pathway was reported to be involved in the increased frequency of CD44+ hepatocellular carcinoma (HCC) stem cells, when co-cultured with TAMs isolated from HCC-bearing patients." (PMID 32397392, 2020). "The constitutive activation of signal transducer and activator of transcription 3 (STAT3) is frequently detected in clinical incidences of hepatocellular carcinoma (HCC) but not in normal human hepatocytes." (PMID 25883212, 2015). "In Multiple Myeloma (MM), but not hepatocellular carcinoma, ChIP and Luciferase gene reporter assays demonstrated IL-6 to regulate BCL3 expression via the binding of STAT3 to the HS4 BCL3 gene enhancer." (PMID 38195591, 2024). "Exosomes derived from hepatocellular carcinoma (HCC) cells can upregulate the expression of PD-L1 on THP-1 cells or RAW264.7 cell-differentiated macrophages, while exosomes treated with melatonin can downregulate the expression of PD-L1, which is related to regulation of the STAT3 signaling pathway." (PMID 34743730, 2021). "Dasatinib, an indirect STAT3 inhibitor against SRC/ABL, significantly facilitated anti-CTLA-4 immunotherapy in head and neck squamous cell carcinoma, while the combined blockade of IL-6 and PD-L1 remarkably inhibited the growth of pancreatic ductal adenocarcinoma and hepatocellular carcinoma (HCC)." (PMID 32972405, 2020). "MiR-589-5p promotes the spheroid formation of CD133+ hepatocellular carcinoma (HCC) cells and their tumorigenicity in vivo by targeting the IL-6 pathway inhibitors SOCS2/5 and PTPNI/11, while it further accelerates tumor chemoresistance via regulation of Stat3 signaling." (PMID 32932969, 2020). "BM-MSCs might activate the IL6/STAT3 signaling pathway and promote cell invasion in hepatocellular carcinoma, but the immunomodulatory role of BM-MSCs on IL17A/IL6/STAT3 was not fully elucidated in liver fibrosis." (PMID 30346985, 2018). "However, when hepatocellular carcinoma (BEL-7402) cells were treated with cucurbitacin B, c-RAF was inhibited without affecting STAT3." (PMID 25674792, 2015). "Hepatocellular carcinoma (HCC) produced by diethylene nitrite (DEN) is considerably more likely to develop when SHP2 is absent, but this is eliminated when SHP2 and STAT3 are both absent at the same time in liver cells." (PMID 38504984, 2024).
glioma (828 papers, 2008 to 2026). A benign or malignant brain and spinal cord tumor that arises from glial cells (astrocytes, oligodendrocytes, ependymal cells). "One compelling example of liposome-based gene therapy involves the targeted silencing of STAT3, a key transcription factor implicated in glioma progression and immune evasion." (PMID 40725021, 2025). "The interaction between NF-κB and STAT3 is associated with tumor progression and the promotion of stemness characteristics in certain cancers, including gliomas." (PMID 40869207, 2025). "High levels of STAT3 expression are linked to a more aggressive subtype of glioma, which is highly resistant to traditional treatments." (PMID 40427146, 2025). "Through systematic analysis of the TCGA database, we detected that the expression of STAT3 correlates with critical indicators of glioma, such as WHO grade, 1p/19q chromosome, and IDH mutation status." (PMID 40265014, 2025). "Our study shows that overexpression of KIAA0040 is linked to glioma malignancy through the JAK2/STAT3 pathway." (PMID 38661644, 2024). "Our previous work showed that FOSL1, transactivated by the STAT3 gene, functions as a tumorigenic gene in glioma pathogenesis and acts as a diagnostic marker and potential drug target in glioma patients." (PMID 38856747, 2024). "The direct targeting of STAT3 by miR-410 has been demonstrated, and the overexpression of STAT3 in glioma tissues has been linked to the epigenetic suppression of miR-410." (PMID 38238515, 2024). "Consistently, in patients with a high risk of recurrence after radiotherapy, there was pronounced STAT3 activation in gliomas." (PMID 36923251, 2023). "An important observation is that the expression of the transforming growth factor beta-induced (TGFBI) by tumor-associated macrophages promotes glioma stem cell maintenance and glioblastoma growth via integrin αvβ5-Src-Stat3 signaling." (PMID 37626776, 2023). "OSM, an IL-6 family cytokine in inducing mesenchymal properties in GBM which mediated signaling contributes to aggressive nature associated with mesenchymal features via STAT3 signaling in glioma cells)." (PMID 38159261, 2023). "In gliomas, STAT3 activation is associated with glioma genesis and transformation to the mesenchymal phenotype." (PMID 37345193, 2023). "The CCK-8 assay showed that downregulating TMEM158 expression inhibited the proliferation of glioma cells, while overexpression of STAT3 rescued the reduced proliferation caused by TMEM158 knockdown." (PMID 34992215, 2022). "We found that the underlying mechanism involves STAT3 activation mediating TMEM158-driven glioma progression." (PMID 34992215, 2022). "Stat3 has been associated with immunological functions but also with growth in several tumors, including gliomas." (PMID 35625843, 2022). "Glioma cell growth, differentiation and motility are regulated also by signal transducer and activator of transcription-3 (Stat3) pathway, which has been shown to be associated with glioblastoma oncogenesis and epithelial-mesenchymal transition (EMT)." (PMID 35303162, 2022). "It has been reported that the expression as well as activation of STAT3 are also associated with the low survival rate and poor prognostic outcome of glioma patients." (PMID 36618071, 2022). "JAK2 plays a central role in phosphorylation of glioma-associated STAT3, a key component of the PI3K-signaling pathway." (PMID 34359681, 2021). "STAT3 activation underlies a host of tumorigenic cellular pathways, the foremost of which is in transcriptionally regulating glioma stem cells (GSCs)—a critically treatment-resistant population of cells that give rise to recurrent disease." (PMID 33498872, 2021). "All together, these observations indicate that increased glioma grading is associated with a rise in CD14+ cells expressing activated STAT3 and PD-L1, suggesting their potential use as blood biomarkers." (PMID 35069595, 2021).
glioma (continued). "Activation of STAT3 is often associated with poor prognosis and chemotherapy resistance in cancer, such as glioma." (PMID 34277607, 2021). "Increasing evidence shows that the activation of IL6-mediated JAK2/STAT3 signaling is frequently associated with glioma, and promotes the cell growth, proliferation, and invasion of glioma cells." (PMID 33858489, 2021). "Signal transducer and activator of transcription 3 (STAT3) has been implicated to play an oncogenic role in various cancers including glioma." (PMID 34195079, 2021). "Meanwhile, to regulate the expression and activation of STAT3 in glioma, the main mechanism underlying miRNA function is through direct binding of the 3′-UTR of the target mRNA." (PMID 34425834, 2021). "Here, we describe a clinically relevant association of CD109 with the STAT3 activation in glioma samples and patient-derived GSCs." (PMID 33986188, 2021). "The combined analysis of 12 trials showed that STAT3/p-STAT3 overexpression in glioma was associated with worse OS (HR = 1.40, 95% confidence interval (CI) = 1.05 ~ 1.86, P = 0.020)." (PMID 33299498, 2020). "Of specific interest was the observation that the IL-33-driven environment activated Stat3 signaling, as indicated by an increase in phosphorylated (p)-STAT3 (pY705), a state that has been associated with glioma progression." (PMID 33020472, 2020). "STAT3 suppression reduced stemness-associated gene expression levels and inhibited colony formation capacity of glioma cells, and the intracranial glioma xenograft growth was effectively impaired." (PMID 33390934, 2020). "We also observed that glioma-derived IL-33 results in an increase in p-STAT3 in both glioma cells and Iba1+ stromal cells, with subsequent loss of p-STAT3 within glioma cells deficient for nuclear IL-33 (ΔNLS)." (PMID 33020472, 2020). "On the contrary, the high expression of STAT3 in glioma is associated with a poor prognosis Phosphorylated STAT3 expression in human gliomas is associated with the pathologic grades and the degree of immune infiltration." (PMID 32823915, 2020). "Noticeably, another study linked phosphorylation of STAT3 to activation of CK2α as an upstream event in human glioma cells." (PMID 31906480, 2020). "The combined analysis of 3 trials showed that STAT3/p-STAT3 overexpression in glioma was associated with better RFS (HR = 0.37, 95%CI = 0.15 ~ 0.95, P < 0.039)." (PMID 33299498, 2020). "Collectively, these results suggest that a combined alteration in membrane lipid metabolism and STAT3 pathway promotes IDH1-mutated glioma malignant progression." (PMID 32218467, 2020). "The combined analysis of 5 trials suggested STAT3/p-STAT3 overexpression in glioma was associated with worse PFS (HR = 2.05, 95%CI = 1.63 ~ 2.58, P < 0.001)." (PMID 33299498, 2020). "Significant associations with high STAT3 expression and reduced survival were identified in the merged Glioma (GBMLGG), Uveal Melanoma (UVM), and Kidney renal clear cell carcinoma (KIRC) cohorts." (PMID 31534498, 2019). "More importantly, Napabucasin treatment obviously inhibited expression of stemness-associated genes including STAT3 and suppressed the spheroid formation of glioma cells in vitro." (PMID 31277685, 2019). "Activation of STAT3 has been shown to enhance proliferation and stemness in glioma-associated-human MSCs46." (PMID 29670257, 2018). "Constitutively active STAT3 frequently occurs in human gliomas and has been implicated in glioma stemness maintenance, chemoresistance, and metastasis." (PMID 29950561, 2018). "In adult glioma, STAT3 activation is associated with increased tumor growth, angiogenesis, therapy resistance and worse patient outcome." (PMID 29164272, 2018). "Previous studies have implicated the STAT3 pathway as a key dysregulated pathway in cancer as evidenced by its constitutive tyrosine phosphorylation in glioma, as well as in breast, colon, kidney and endometrial cancers." (PMID 29774125, 2018).
glioma (continued). "Previous studies have shown that STAT3 activation causes changes to colorectal cancer, glioma cells, and dendritic cells." (PMID 29596388, 2018). "In contrast, silencing of IL-13Rα2 in EGFRvIII-positive glioma cells and primary culture caused a significant reduction in STAT3 activation." (PMID 29203859, 2017). "Transcription factor STAT3, which is upregulated in glioma-associated microglia, is a promising target for molecular intervention." (PMID 26217588, 2015). "In high-grade glioma, elevated pSTAT3 levels have been linked to chemo-resistance, and blockade of STAT3 signalling sensitizes glioma cells to chemotherapy, thus providing a rationale for the use of targeted therapies against STAT39." (PMID 26542452, 2015). "A close association between STAT3 activation and glioma growth and vascularization has been reported previously, and activation of STAT3 has been directly correlated with VEGF production." (PMID 25789853, 2015). "Glioma aggressiveness is associated with a mesenchymal phenotype that is regulated by the C/EBPβ and STAT3 transcription factors." (PMID 25893706, 2015). "PTPRD was shown to be a tumor suppressor, as loss of PTPRD caused aberrant STAT3 activation in gliomas, resulting in glioma progression." (PMID 26079428, 2015). "Gain of function mutations result in constitutive activation of STAT3 in glioma cells, making STAT3 an attractive target for inhibition in cancer therapy." (PMID 24518612, 2014). "Activation of STAT3 has been implicated in tumor activation through the production of anti-apoptotic and glioma stem-cell maintenance factors, pro-invasive enzymes, and angiogenic elements such as VEGF." (PMID 24518612, 2014). "Nevertheless, some studies show that STAT3 also participates in terminal differentiation and apoptosis of various cell lines and in glioma with phosphatase and tensin homolog (PTEN)-deficient genetic backgrounds." (PMID 24518612, 2014). "The preceding data provided a rationale for attempting pharmacologic avenues to increase STAT3 in glioma cells, rendering them more susceptible to oHSV therapy." (PMID 23936533, 2013). "Iripallidal (i) induced apoptosis, (ii) inhibited Akt/mTOR and STAT3 signaling, (iii) altered molecules associated with cell cycle and DNA damage, (iv) inhibited telomerase activity and colony forming efficiency of glioma cells." (PMID 20576128, 2010). "In gliomas, cytokines, such as interleukin (IL)-6 (IL-6) and epidermal growth factor, can cause subsequent phosphorylation and activation of STAT-3." (PMID 19900287, 2009). "STAT3 has been reported to regulate a range of stemness-associated transcription factors, including Nanog, Sox2, and Oct4, in glioblastoma, thereby facilitating the formation and maintenance of glioma stem-like cells (GSCs)." (PMID 40759869, 2025). "Furthermore, glioma patients with IDH wild-type status exhibited higher STAT3 expression compared to those with IDH mutations (Mut) (p < 0.001)." (PMID 40265014, 2025). "Since STAT3 has been reported as a TF associated with glioma stemness, we next tested whether STAT3 promoted CYP3A5 transcription." (PMID 39754188, 2025). "In line with our hypothesis, the levels of p-STAT3 were remarkably reduced in glioma-bearing hemispheres of SorLA-deficient mice as compared to WTs." (PMID 38499808, 2024). "The results showed that notopterol had anti-glioma effects which decreased STAT3 activity and alleviated neuropsychiatric symptoms by inhibiting tumor-associated inflammation through modulation of the STAT3/NF-κB pathway in mice with glioma." (PMID 39064831, 2024). "Furthermore, we confirmed that the upregulation of STAT3 levels is negatively associated with decreased miR-410 expression in glioma tissues." (PMID 38238515, 2024). "Moreover, high levels of phosphorylated-STAT3 (pSTAT3) are associated with more severe gliomas and poorer patient outcomes." (PMID 36969167, 2023).
glioma (continued). "In Nano-DOX-BMDM-treated mice, Nano-DOX can be delivered to GBM via GBM-associated immune cells (e.g., macrophages) to inhibit STAT3 activation in glioma cells and reduce their export of IL-6 to astrocytes, thereby abolishing feedback activation of astrocytes to glioma cells." (PMID 36923251, 2023). "Aberrant STAT3 activation is associated with radiation resistance in gliomas." (PMID 36923251, 2023). "In glioma patients, high STAT3 signaling is associated with high E2F1 and H2AZ2 expression." (PMID 35058574, 2022). "Therefore, we mimicked the tumor microenvironment using co-cultured glioma C6 cells and rat MSCs, aiming to assess the proliferation and migration of MSCs and the associated effects of Stat3 in this process." (PMID 36295083, 2022). "Similarly, it has been observed that glioma-initiating cells proliferation, and tumor growth are intrinsically linked to STAT3 up-regulation." (PMID 33544704, 2021). "Additionally, increased cytokine expression caused by interactions between microglia and glioma cells can activate endothelial Jak / Stat3 signaling, resulting in increased vascular permeability in vitro." (PMID 34425907, 2021). "Studies showed that STAT3 signaling was associated with chemoresistance of TMZ in gliomas." (PMID 34961815, 2021). "Interestingly, pacritinib was also shown to decrease the amount of miR-21-enriched exosomes released from tumor-associated macrophages, reducing an exogenous source of STAT3 upregulation in glioma cells." (PMID 33498872, 2021). "The activation of STAT3 is associated with poor prognosis in patients with glioma." (PMID 34503167, 2021). "This study aimed at investigating the association between STAT3/p-STAT3 and glioma prognosis." (PMID 33299498, 2020). "In conclusion, our study suggested that STAT3/p-STAT3 is associated with poor prognosis in patients with glioma, which indicated that STAT3/p-STAT3 might be a valuable prognostic biomarker and a promising therapeutic target for glioma." (PMID 33299498, 2020). "Mechanistically, BMX bypasses the suppressor of cytokine signaling 3 (SOCS3)-mediated inhibition of JAK2, whereas targeting of the BMX dampens the JAK2-mediated STAT3 activation, underlying a new molecular basis in which to specifically eliminate the glioma stem cells." (PMID 31130822, 2019). "To examine whether Smad6 contributes to STAT3 activation, we first analyzed proteins downstream of STAT3 associated with glioma stemness, including c-jun, CCND1, and Sox2." (PMID 29950561, 2018). "In gliomas, loss of PTPRD could cause aberrant activation of STAT3 and is closely associated with glioma progression." (PMID 27738328, 2016). "Moreover, accumulating evidence shows that the STAT3 is highly expressed in manlignant gliomas and strongly linked to tumor angiogenesis and metastasis." (PMID 25789853, 2015). "The results revealed that saw palmetto extract markedly inhibited the proliferation of human glioma cells and the underlying mechanism may be associated with the inhibition of signal transducer and activator of transcription 3 (STAT3) phosphorylation." (PMID 25009620, 2014). "The results suggest that chronic IL-1 production by glioma can cause sustained Stat3 activation." (PMID 25054228, 2014). "The RAGE pathway may play an important role in STAT3 induction in glioma-associated microglia and macrophages, a process that might be mediated through S100B." (PMID 24521265, 2013). "Likewise, several other groups have reported STAT3 to be associated with migration and invasion in glial as well as non-glial tumors." (PMID 20840775, 2010). "Additionally, the interactions of Epidermal Growth Factor Receptors (EGFR)/Signal transducer and activator of transcription 3 (STAT3) or the epidermal growth factor receptor variant III (EGFRvIII)/STAT3 signaling axes with COX2 downstream pathways contributes to glioma angiogenesis." (PMID 35757736, 2022). "Besides cell proliferation, STAT3 has been linked to migration and invasion of glioma cells." (PMID 35409080, 2022).